KRTAP15-1 (keratin associated protein 15-1)
Description:
In the hair cortex, hair keratin intermediate filaments are embedded in an interfilamentous matrix, consisting of hair keratin-associated proteins (KRTAP), which are essential for the formation of a rigid and resistant hair shaft through their extensive disulfide bond cross-linking with abundant cysteine residues of hair keratins. The matrix proteins include the high-sulfur and high-glycine-tyrosine keratins.
Synonyms: KAP15.1
Tractability: No criterion of Open Targets' tractability assessment is met for any kind of drug.
Gene: Protein-coding gene on chromosome 21 (30,440,275 to 30,440,869, forward strand). Ensembl gene ENSG00000186970.
Pathways (Reactome):
Developmental Biology: Keratinization
Gene Ontology:
Molecular function: protein binding
Cellular component: cytosol
Genetic constraint (gnomAD): Loss-of-function variants: 0 observed, 1.02 expected, observed/expected ratio (o/e) 0, 90% interval 0 to 1.72. That is too few expected variants to judge how well the gene tolerates losing a copy. Missense variants: 181 observed, 164.6 expected, observed/expected ratio (o/e) 1.1, 90% interval 0.97 to 1.24. Synonymous variants: 65 observed, 63.44 expected, observed/expected ratio (o/e) 1.02, 90% interval 0.84 to 1.26.
Homologues: Orthologues: macaque KRTAP15-1 (86% identical), mouse Krtap15-1 (54% identical). Paralogues in human: KRTAP13-2 (60% identical), KRTAP13-1 (58% identical), KRTAP13-3 (50% identical), KRTAP13-4 (49% identical), KRTAP11-1 (31% identical), KRTAP26-1 (23% identical), KRTAP27-1 (23% identical), KRTAP25-1 (18% identical).